HMGB1 (high mobility group box 1)
Diseases named in the same sentence as HMGB1 in open-access papers (continued):
Sharing a sentence is not in itself a finding about the gene and the disease.
glioma (continued). "Since HMGB1 is a well-established oncogene promoting tumorigenesis in many cancers, our data support the notion that circ_0008285 overexpression enhances the HMGB1 protein level through sponging miR-384 to support the malignancy of glioma cells." (PMID 37575469, 2023). "However, necrotic glioma cells can release HMGB1 after it has translocated from the nucleus to the cytosol." (PMID 38132142, 2023). "This indicates that miR-665 acts as a tumor suppressor in glioma, is a good candidate prognostic biomarker, and may be used together with HMGB1 as a novel therapeutic target." (PMID 37894282, 2023). "We further demonstrated that miR-384 could negatively target HMGB1 to regulate the malignancy of glioma cells." (PMID 37575469, 2023). "In gliomas, tumour-infiltrating neutrophils could produce neutrophil extracellular traps to promote glioma progression via the HMGB1/RAGE/IL-8 axis." (PMID 37566174, 2023). "This suggests that HMGB1 secreted from tumor is a key regulator for angiogenesis and that glioma and endothelial cells may have reciprocal effects through HMGB1." (PMID 37210579, 2023). "To evaluate gene expression changes in oHSV-infected cells that significantly affected pathways involved in HMGB1 signaling, we analyzed RNA sequencing results from oHSV (rHSVQ)-infected U87ΔEGFR glioma cells using a Kyoto Encyclopedia of Genes and Genomes (KEGG) enrichment analysis." (PMID 36789106, 2023). "It has also been found that hyperglycemia may participate in glioma growth and suppress anti-tumor immune responses by activating the HMGB1–RAGE axis." (PMID 37759870, 2023). "Several previous studies have been shown that exogenous HMGB1 promotes pro-survival autophagy and stimulates the tumor growth of gliomas and esophageal squamous carcinoma, in addition to enhancing the chemoresistance of tumor cells in leukemic and bladder cancers." (PMID 37880798, 2023). "miR-384 tended to be downregulated, whereas HMGB1 showed upregulation in glioma tumor samples." (PMID 37575469, 2023). "Our study revealed circ_0008285 as a novel oncogenic factor in glioma through modulating the miR-384/HMGB1 pathway, suggesting that targeting circ_0008285 could serve as a strategy for glioma management." (PMID 37575469, 2023). "The level of HMGB1 expression in gliomas is three-fold higher than in normal brains, and during inflammation, HMGB1 may be released extracellularly from neurons, glial, or endothelial cells." (PMID 38003396, 2023). "Finding miR-339-5p inhibitory functions in glioma through PTP4A1/HMGB1 pathway." (PMID 35872698, 2022). "On the one hand, glioma is a highly pro-inflammatory tumor since the abundant secretion of pro-inflammatory factors, such as IL-1β, IL-6, and high mobility group box protein (HMGB1) through the autocrine or paracrine mechanism accelerates tumor growth." (PMID 35990696, 2022). "Moreover, the upregulation of high-mobility group box 1 protein (HMGB1) was reported to weaken the inhibition of glioma growth caused by the knockdown of LINC00662, suggesting that HMGB1 should be considered an miR-107 target." (PMID 34354995, 2021). "In this study, we demonstrated that YAP promotes glioma progression by enhancing HMGB1-mediated autophagy, which indicates that YAP-HMGB1 signaling axis may be a molecular therapeutic target for GBM." (PMID 33726796, 2021). "This work suggests that successful targeting of HMGB1 may improve glioma treatment responses to TMZ." (PMID 34975408, 2021). "Blocking HMGB1 reduced N18 neuroblastoma and C6 glioma cell migration in a dose-dependent manner." (PMID 33748118, 2021). "Finally, we showed that the effect of HMGB1 on glioma cells was mediated by TLR2, which activated Wnt/β-catenin signaling to promote GSCs." (PMID 33614649, 2021). "Moreover, phosphorylation of ERK1/2 and IκB mediated by NETs or HMGB1 was abrogated by blocking RAGE on glioma cells." (PMID 32296583, 2020).
glioma (continued). "Taken together, these results suggested that HMGB1 could promote the formation of GSCs by primary glioma cells via TLR9 and NEAT1." (PMID 32843056, 2020). "Various studies investigate the role of HMGB1 in glioma tissue." (PMID 32684831, 2020). "Moreover, functional tests revealed that HMGB1 suppression represses the proliferation invasion of glioma cells in vitro." (PMID 32913464, 2020). "Moreover, correlation analysis revealed that HMGB1 positively correlates with the expression of LINC00662 in glioma tissues." (PMID 32913464, 2020). "Analysis of data extracted from TCGA revealed that glioma tissues have elevated levels of HMGB1." (PMID 32913464, 2020). "Multiple studies have shown that HMGB1 drives cancer development, including glioma 28-30." (PMID 32913464, 2020). "Interestingly, several studies reported that miR-142/HMGB1 axis play a key role in various human cancers, such as glioma and cervical cancer (CC)." (PMID 33628189, 2020). "The results revealed that more HMGB1 protein occupies the CpG sites of the SASH1 gene in C6 glioma cells than in astrocytes and that this increased occupation may contribute to the methylation of these sites in C6 cells." (PMID 31138780, 2019). "A previous study has reported that HMGB1 promotes the proliferation and migration of glioma cells." (PMID 26337661, 2015). "Besides, Western blot analysis revealed that HMGB1 was significantly up-regulated in glioma tumors compared with those in matched adjacent tissues." (PMID 25772485, 2015). "In glioma cells, inhibition of HMGB1 was found to suppress the cell growth and migration in vitro." (PMID 25772485, 2015). "Taken together, our data suggested that miR-129-2 functions as a tumor suppressor in glioma cells by directly targeting HMGB1 and is down-regulated by DNA methylation, which may provide a novel therapeutic strategy for treatment of glioma." (PMID 25772485, 2015). "HMGB1 may be an important factor involved in the processes of glioma occurrence and development, and may seriously affect the prognosis of patients with glioma." (PMID 25574225, 2015). "The expression of HMGB1 in glioma tissue was higher than that in normal tissue (P<0.05)." (PMID 25574225, 2015). "Therefore, treatments targeting HMGB1 are expected to become a novel therapeutic approach towards the treatment of patients with glioma." (PMID 25574225, 2015). "Taken together, the validated involvement of miR-129-1/HMGB1 link in glioma cells may provide potential to use miR-129-2 and HMGB1 as therapeutic targets for glioma." (PMID 25772485, 2015). "Detecting HMGB1 in human gliomas may be useful for assessing the degree of malignancy, and HMGB1 would appear to be a promising target in the clinical management of patients with glioma." (PMID 25574225, 2015). "A previous study has reported that HMGB1 promote the proliferation and migration of glioma cells." (PMID 26337661, 2015). "Taken together, our data suggest that miR-129-2 may inhibit HMGB1 expression by directly targeting its 3′UTR in glioma cells." (PMID 25772485, 2015). "However, in the 65 glioma samples the HMGB1 positive expression rate was 76.9% (50/65), which was higher than that in the normal brain tissue (P<0.05)." (PMID 25574225, 2015). "The inhibition of HMGB1 gene expression may inhibit the growth and proliferation of glioma cells and promote apoptosis; overexpression of HMGB1 may promote the growth and proliferation of glioma cells and inhibit apoptosis." (PMID 41300698, 2025). "Notably, the up-regulated expression of HMGB1 may play key roles in the occurrence, development, invasion and metastasis of gliomas." (PMID 41300698, 2025). "Furthermore, AGEs can promote tumor growth by activating the receptor of AGEs (RAGE), as recent studies have shown that inducing RAGE expression in diabetic mice resulted in increased tumor growth in the GL261 glioma model via the upregulation of High Mobility Group Box 1 (HMGB1)." (PMID 38067186, 2023).
glioma (continued). "We next investigated whether the promotion effect of YAP on glioma growth was mediated by HMGB1." (PMID 33726796, 2021). "Taken together, these data indicated that HMGB1 could be a target of miR-107 in glioma." (PMID 32913464, 2020). "Moreover, low miR-107 levels negatively correlated with high HMGB1 expression in glioma." (PMID 32913464, 2020). "LINC00662 might exert its functions by regulating the miR-107/HMGB1 axis in glioma." (PMID 32913464, 2020). "HMGB1 may also play an important role in human gliomas, however related studies are rare." (PMID 25574225, 2015). "NETs produced by tumor-infiltrating neutrophils (TINs) mediate the communication between glioma progression and TME by regulating the HMGB1/RAGE/IL-8 axis." (PMID 41019086, 2025). "The HMGB1/RAGE/IL‐8 axis plays a crucial role in neutrophil recruitment into the TME and NETosis as HMGB1 was found to bind the RAGE receptor on glioma cells, activating NF‐κB and upregulating IL‐8 expression—an influential neutrophil chemoattractant." (PMID 40145271, 2025). "The HMGB1/RAGE axis has been found to affect proliferation in cervical cancer, glioma, and clear cell carcinoma through the Mitogen-Activated Protein Kinase (MAPK) signaling pathway." (PMID 38529373, 2024). "Hypoxia-induced HMGB1 activates the RAGE-dependent ERK1/2 signaling pathway, maintaining glioblastoma proliferation, regulating glioma stem cells’ self-renewal, and further promoting tumor progression." (PMID 38529373, 2024). "Simultaneously, TAMs respond to lactate stimulation by secreting HMGB1 through the activation of GPR65, further enhancing glioma progression." (PMID 38576043, 2024). "Mechanistically, the lactate-signal activated GPR65 on TAMs, triggering the secretion of HMGB1 through the cAMP/PKA/CREB signaling pathway, ultimately facilitating glioma progression." (PMID 38576043, 2024). "We demonstrated that pz I-PDT and pz III-PDT can act as efficient ICD inducers when applied to glioma GL261 cells, facilitating the release of two crucial DAMPs (ATP and HMGB1)." (PMID 37896190, 2023). "High mobility group box 1 (HMGB1), one of the DAMPs, was reported to induce epithelial-mesenchymal transition (EMT) of glioma cells." (PMID 37465363, 2023). "The NDV infection of glioma cells induced the upregulation of DAMPs, such as calreticulin (Ecto-CRT), heat-shock proteins (HSP), high mobility group box 1 (HMGB1), and ATP." (PMID 35327364, 2022). "Using the U87MG (PD-L1high) immunohumanized mouse glioma model in vivo, the ICD was measured by staining for HMGB1 and HSP-70 using either OVTs alone or in combination with blocking the PD-1/PD-L1 interaction." (PMID 36077380, 2022). "We had already characterized PS-PDT in our previous work and showed that glioma GL261 cells subjected to PS-PDT undergo ICD with the emission of the three major DAMPs (CRT, ATP, and HMGB1), thereby inducing activation and maturation of DCs in vitro." (PMID 36539408, 2022). "YAP promoted glioma progression by enhancing HMGB1-mediated autophagy, indicating that YAP-HMGB1 axis was a feasible therapeutic target for GBM." (PMID 33726796, 2021). "We showed that ENPDOX induced apoptosis and ICD of glioma cells in vitro with increased CRT surface exposure and increased release of HMGB1 and ATP." (PMID 34589592, 2021). "Next, examined by western blotting, we found a positive correlation between YAP and HMGB1, YAP and LC3-II expression in high grade glioma samples, in line with CGGA database analysis." (PMID 33726796, 2021). "In our system, by using three cohorts of glioma samples, we found that YAP and HMGB1 expression is positively correlated with each other, and were prognostic for clinical GBM, in line with our results in vitro." (PMID 33726796, 2021). "Here, we examined the role of LINC00662 in glioma and found that it promotes glioma deterioration by regulating the LINC00662/miR-107/HMGB1 axis, suggesting its potential as a novel therapeutic target against glioma." (PMID 32913464, 2020).
glioma (continued). "To further demonstrate the binding of HMGB1 to RAGE on glioma cells, we incubated LN229 cells with NETs or recombinant HMGB1 (1 μg/mL, Sigma, St." (PMID 32296583, 2020). "Thus, LINC00662 could accelerate glioma deterioration by modulating the miR-107/HMGB1 axis." (PMID 32913464, 2020). "With a similar consideration, we have shown that HMGB1, a DAMP frequently generated in TME by tumor/TME cells under stress, also promoted GSCs formation from primary glioma cells." (PMID 32843056, 2020). "In 63 adult patients with gliomas and 31 healthy controls, the expressions of TREM-1 and TREM-2 on CD14+ blood cells (method: flow cytometry) and the levels of soluble sTREM-1, HMGB1, IL-6, and IL-10 (Elisa tests) were analyzed." (PMID 32684831, 2020). "In an orthotopic murine glioma model it was demonstrated that NDV virotherapy induces ICD with its molecular determinants such as calreticulin, HSP and high mobility group box-1 (HMGB1, amphoterin)." (PMID 28531117, 2017). "HMGB1 is also necessary for the transfilter migration of glioma cells and that migration is inhibited by antibodies against the RAGE-binding domain of HMGB1." (PMID 24710526, 2012). "Bioinformatics analysis further revealed that HMGB1 levels were higher in glioma tissues than in non-tumor tissues, and elevated intracellular HMGB1 expression correlated with poor prognosis." (PMID 40688353, 2025). "HMGB1 derived from NETs binds to RAGE and activates the nuclear factor κB (NF-κB) signaling pathway, which is also stimulated by NETs and promotes interleukin 8 (IL-8) secretion in glioma." (PMID 41019086, 2025). "In addition to enhancing granulopoiesis, gliomas can recruit neutrophils to the TME through expression of high levels of IL-8, under stimulation of IL-1, TNF⍺, and high-mobility group box 1 (HMGB1) derived from NETs." (PMID 38254796, 2024). "More importantly, HMGB1 expression showed a positive correlation with circ_0008285 and a negative correlation to miR-384 in glioma specimens." (PMID 37575469, 2023). "A mouse xenograft model carrying human glioma cells demonstrated invasion features at the tumor boundary without ITN after treatment of HMGB1, a DAMPs released from dead cells." (PMID 37465363, 2023). "In vitro, PDT treatment of glioma cells was shown to induce surface exposure of the DAMPs CRT, HSP70, and HSP90 in addition to an increase in extracellular DAMPs adenosine triphosphate (ATP) and high mobility group box 1 (HMGB1)." (PMID 36839652, 2023). "considered that HMGB1-activated dendritic cells, loaded with glioma antigens, migrate to cervical lymph nodes to stimulate a systemic CD8+ T cells cytotoxic immune response against glioma and induce immunological memory." (PMID 35832539, 2022). "Compared to non-tumor and low-grade glioma, mRNA levels of HMGB1 were significantly increased in GB." (PMID 35193644, 2022). "In an in vitro BBB assay, we showed that ENPDOX was able to penetrate mouse endothelial cells and induce apoptosis and ICD of glioma cells, including increased surface CRT exposure, HMGB1 secretion and ATP release, manifestations that are characteristics of ICD." (PMID 34589592, 2021). "According to the data of High Grade Glioma patients with follow-up information (n = 39), the clinical implications of these findings were highlighted by the determination of the survival time of patients being inversely correlated with YAP and HMGB1 staining." (PMID 33726796, 2021). "Down-regulation of HMGB1 abolished the promoting effect of YAP on autophagy and glioma growth." (PMID 33726796, 2021). "We found a negative correlation of the serum levels of HMGB1 in glioma patients with both percentages of CD14+ TREM-1+ cells (P = 0.049) and TREM-1/TREM-2 ratio (P = 0.004)." (PMID 32684831, 2020). "Consistently, HMGB1 but not CpG-ODN increased the formation of tumor spheres by primary glioma cells." (PMID 32843056, 2020).
glioma (continued). "In conclusion, our results indicate that LINC00662 acts as an oncogene in glioma by modulating the miR-107/HMGB1 axis, suggesting that LINC00662 could be a novel therapeutic target for glioma treatment." (PMID 32913464, 2020). "In our present work, we found that the mesh-like structure of NETs was decorated with HMGB1, and the externalized HMGB1 interaction with RAGE on glioma cells led to the activation of the transcription factor NF-κB, which has been reported to be a key transcription factor affecting IL-8 expression." (PMID 32296583, 2020). "Moreover, HMGB1 and SCD1 have been demonstrated to be closely correlated with drug resistance in glioma." (PMID 31118022, 2019). "When all patients with glioma were considered together, the survival rate of patients with HMGB1-negative tumors was significantly higher than that of patients with HMGB1-positive tumors (P=0.026)." (PMID 25574225, 2015). "Luciferase reporter assay found that miR-129-2 could directly target high-mobility group box 1 (HMGB1) and inhibit its expression in glioma cells." (PMID 25772485, 2015). "The upregulation of TLR4 and HMGB1 is synergistic and results in the increase of HLA-G, a non-classical HLA class I antigen that participates in glioma immune evasion." (PMID 25411122, 2014). "Additionally, high-mobility group box 1 (HMGB1), derived from neutrophil extracellular traps (NETs), binds to the receptor for advanced glycation end products (RAGE) in glioma tissue, activating the NF-κB signaling pathway and promoting IL-8 secretion, thereby enhancing neutrophil infiltration." (PMID 38732975, 2024). "The HMGB1/RAGE/IL-8 axis plays a crucial role in neutrophil recruitment into the tumor microenvironment (TME) and NETosis as HMGB1 was found to bind the RAGE receptor on glioma cells, activating NF-κB and upregulating IL-8 expression—an influential neutrophil chemoattractant." (PMID 38474175, 2024). "Toll-like receptor 2, one of the HMGB receptors, is believed as correlation with NETs production, and HMGB1-mediated TLR2 signaling plays a critical role in eliciting glioblastoma regression, However, further studies are still needed to clarify the protumor and antitumor functions of NETs in glioma." (PMID 35711434, 2022). "Similarly, given that NETs can promote the proliferation and invasion of glioma though the binding of HMGB1 and RAGE, it is also possible that the administration of anti-HMGB1 antibodies to glioma patients can inhibit the deterioration and progression of tumors induced by NETs." (PMID 34336122, 2021). "Consequently, the inhibition of HMGB1 levels in CM from shNC TAMs using glycyrrhizin led to a notable reduction of tumor cell proliferation, while the exogenous addition of rHMGB1 rescued the enhanced growth of glioma cells in GPR65-silenced TAMs." (PMID 38576043, 2024). "However, a report claimed that HMGB1 expression does not correlate with the prognosis in glioma." (PMID 37575469, 2023). "However, we currently could not clarify ADV infection or HMGB1 treatment promotes dedifferentiation of differentiated glioma cells, or they promote the proliferation of rare GSCs in the stocks of patient-derived primary glioma cells." (PMID 32843056, 2020). "This follows release of HMGB1, a TLR2 agonist that activates dendritic cells and stimulates dendritic cells loaded with glioma antigens to migrate to the cervical lymph nodes to prime a systemic CD8+ T cytotoxic killing of glioma cells without causing brain toxicity and autoimmunity." (PMID 31069169, 2019). "Interestingly, as a known positive regulator, CCL19 demonstrated relatively more negative correlations in glioma, with the most significant negative correlations with VEGFA, CD276, and HMGB1." (PMID 40714831, 2025).
glioma (continued). "IL- 1β secreted from glioma cells was found to be responsible for the activation of TLR-4 and upregulation of high mobility group box 1 (HMGB1) protein, which eventually results in the increase of HLA-G, a non-classical HLA class I antigen that contributes to glioma immune evasion response." (PMID 34439380, 2021).